IP6K1 (inositol hexakisphosphate kinase 1)
Diseases named in the same sentence as IP6K1 in open-access papers (continued):
Sharing a sentence is not in itself a finding about the gene and the disease.
tumor (continued). "Our data indicate that host IP6K1 acts as a tumor suppressor to regulate anti-tumor immune activities and control the recruitment and activation of cytotoxic T cells to the primary tumor through reprogramming tumor-immune control, and loss of this pathway increases tumor progression." (PMID 35308129, 2022). "Since our approach using syngeneic tumor model demonstrate that targeting IP6K1 from the host promotes tumor growth, we believe that the host IP6K1 as a tumor suppressor may contribute to improving the host immune response against tumor progression." (PMID 35308129, 2022). "However, regarding tumor formation and progression, the role of host IP6K1 in this pathology remains poorly understood." (PMID 35308129, 2022). "Consequently, a significantly reduced amount of CD8+ killer T cells was observed in the tumor tissues, when host IP6K1 was deleted." (PMID 35308129, 2022). "By flow cytometric analysis we showed that tumors in IP6K1 KO mice contain high levels of CD11b+Gr1 + IL10+ myeloid cells (e.g., neutrophils, monocytes) and lower infiltration of M1-polarized tumor-associated macrophage (TAM), dendritic cells, and CD8+ killer T cells into tumors." (PMID 35308129, 2022). "Examination of whether IP6K1 in T cells could directly influence their effector functions for anti-tumor activities is also required." (PMID 35308129, 2022). "In the present study, we investigated whether host IP6K1 KO could control tumor growth using a syngeneic MC38 model which is a murine colon adenocarcinoma tumor model on the C57BL/6 background." (PMID 35308129, 2022). "Notably, infiltration of both antigen-presenting dendritic cells and CD8+ cytotoxic T lymphocytes into the tumor tissues was remarkably abrogated in IP6K1 KO condition." (PMID 35308129, 2022). "In addition, increased levels of IL10+ myeloid cells (e.g., neutrophils or myeloid-derived suppressor cells), as well as lowered anti-tumor M1 TAMs from tumor tissues in IP6K1 KO mice, appear to be another major contributing factor to avoid immune surveillance." (PMID 35308129, 2022). "However, gross and microscopic examination of liver, kidney, spleen, thymus and lymph nodes from four individual 2 year old male Ip6k1+/+ and Ip6k1−/− mice revealed no lesions, suggesting that the loss of IP6K1 does not result in spontaneous tumor formation." (PMID 27140681, 2016). "Here, we evaluated the role of host IP6K1 by using a syngeneic MC38 model, a commonly used preclinical model to investigate the complex actions of tumor cell-intrinsic and extrinsic factors in the control of tumorigenesis." (PMID 35308129, 2022). "In IP6K1 knockout (KO) mice, the growth of MC38 tumor cells was markedly accelerated and host survival was significantly shortened compared with wild-type (WT)." (PMID 35308129, 2022). "First, we measured CD11b+Gr1+ myeloid cells and found no apparent changes in tumor tissues grown from both WT and IP6K1 KO mice." (PMID 35308129, 2022). "Collectively, these results indicated the lack of IP6K1 in mice accelerated tumor growth and shortened host survival, suggesting the in vivo role of host IP6K1 as a tumor suppressor." (PMID 35308129, 2022). "Furthermore, major activities of Akt and other inflammation signaling events were similar between in vitro polarized IP6K1 KO and WT BMDMs, which further indicates that IP6K1 deletion may elicit its impact on TAMs throughout the in vivo tumor microenvironment but not in vitro culture conditions." (PMID 35308129, 2022). "Although we also observe reduced migration and invasion properties in IP6K1 depleted HCT116 cells, there is no reduction in tumor volume." (PMID 27140681, 2016). "The distinct functions of IP6K1 and IP6K2 in tumor development may also arise from their differential effects on cell proliferation, with IP6K2 knockout HCT116 cells exhibiting delayed growth, and IP6K1 depleted cells exhibiting no change in doubling time." (PMID 27140681, 2016).
cardiovascular diseases (1 paper, 2024). "Taken together, these pieces of evidence support IP6K1 as a potential therapeutic target for metabolic dysfunction and cardiovascular diseases." (PMID 39643078, 2024). "However, the roles of IP6K1 and its derived 5PP-InsP5 in metabolic dysfunction-related cardiovascular diseases have not been demonstrated." (PMID 39643078, 2024).
infection (1 paper, 2022). The state of being infected such as from the introduction of a foreign agent such as serum, vaccine, antigenic substance or organism. "Neurons were transfected at the time of plating with VGLUT1-pH or VGLUT2-pH and infected at DIV7 with lentiviruses expressing constructs containing either IP6K1- or IP6K3-specific shRNA hairpins, along with mTagBFP as a reporter to monitor infection efficiency." (PMID 35936490, 2022).
IP6K1 also shares sentences with these, for which no sentence is quoted: Hyperinsulinemia (3 papers); non-alcoholic fatty liver disease (2); acute pancreatitis (1); alcoholic cirrhosis (1); Alzheimer disease (1); bone disorder (1); cardiac ischemia (1); cerebral infarction (1); Cirrhosis (1); cognitive deficits (1); epithelial dysplasia (1); Hyperglycemia (1); ischemia (1); liver disease (1); myocardial infarction (1); non-alcoholic fatty liver (1); osteoporosis (1); pneumonia (1); spinocerebellar ataxia (1); sterility (1); Thromboembolism (1).